TINCR (TINCR ubiquitin domain containing)
Diseases named in the same sentence as TINCR in open-access papers (continued):
Sharing a sentence is not in itself a finding about the gene and the disease.
breast cancer (continued). "In particular, we found that the lncRNA was also involved in regulation of cell differentiation in three data sets including breast cancer, prostate cancer, and psychiatric disorders, which was consistent with a previous study that TINCR can control tissue differentiation." (PMID 25815337, 2015). "Tissue differentiation inducing non-protein coding RNA (TINCR), a long non-coding RNA, as an oncogenic gene associated with the progression of various malignant tumors, including breast cancer; however, the role of TINCR in tumor immunity, especially in breast cancer, remains unclear." (PMID 36725842, 2023). "In addition, we used rescue experiments to explore whether OAS1 is involved in the carcinogenic effect of TINCR in breast cancer." (PMID 33649294, 2021). "In breast cancer, there is also an upstream regulatory mechanism in which the INFγ–STAT1 signaling axis promotes TINCR transcription in the breast." (PMID 37835376, 2023). "In conclusion, this study has revealed that TINCR promotes tumorigenesis through a STAT3–TINCR–EGFR-feedback loop by recruiting DNMT1 and acting as a ceRNA in human breast cancer." (PMID 33446634, 2021). "We also examined the relationship between TINCR and EGFR protein expression in 120 breast-cancer samples from HMUCC, and the results showed that the EGFR level was higher in TINCR high-expression tissues than in TINCR low-expression tissues." (PMID 33446634, 2021). "TINCR was found to be upregulated and positively correlated with EGFR expression in human breast cancer." (PMID 33446634, 2021). "The function of TINCR in CRC appeared to be tumor-suppressive, which is different from how it functioned in gastric cancer, breast cancer and hepatocellular carcinoma." (PMID 32681722, 2020). "TINCR was aberrantly up-regulated by SP1, which in turn stimulated cell proliferation, anchorage-independent growth and suppressed cell apoptosis in breast cancer." (PMID 29614984, 2018). "Taken together, TINCR promotes tumourigenesis partly via TINCR-MiR-125b-ERBB2 axis and its negative regulation of apoptosis pathway in breast cancer." (PMID 28738804, 2017). "From our sequencing results and TCGA data, TINCR, LINC00511, and PPP1R26-AS1 were identified and were found to represent HER-2, triple-negative and luminal B subtypes of breast cancer, respectively." (PMID 28738804, 2017). "Another interesting example is TINCR, which is activated by IFN-γ/STAT1 signaling in breast cancer." (PMID 41154428, 2025). "In examining the upstream regulatory mechanism of TINCR in breast cancer, we found that IFN-γ stimulation can activate downstream STAT1 signaling and that STAT1 migrates to the nucleus to promote the transcription of TINCR, thus regulating the expression of downstream miR-199a-5p, USP20, and PD-L1." (PMID 36725842, 2023). "In terms of mechanism, TINCR can act as a ceRNA to sponge miR-503-5p, thereby up-regulating downstream EGFR expression and downstream signal JAK2 and STAT3 conduction, ultimately leading to a malignant phenotype of breast cancer." (PMID 37901333, 2023). "For instance, the lncRNA TINCR may operate as a competitive endogenous RNA in human breast cancer by recruiting DNMT1 and driving carcinogenesis through the STAT3-TINCR-EGFR signaling axis." (PMID 36157234, 2022). "To validate the result, we analyzed 250 tissue specimens—125 breast-cancer and 125 adjacent normal tissues—from Harbin Medical University Cancer Center (HMUCC), and we found that TINCR was upregulated in breast-cancer tissues relative to the expression in normal tissues." (PMID 33446634, 2021). "We have verified that TINCR can regulate OAS1 in breast cancer, while the mechanism was still not clear." (PMID 33649294, 2021). "In addition, TINCR overexpression competed with miR-7 and facilitated KLF4 expression, which in turn regulated cell proliferation, migration, and invasion in breast cancer." (PMID 34527584, 2021).
breast cancer (continued). "Until now, the expression and potential linkage to tumorigenesis of TINCR in breast cancer has not been fully investigated." (PMID 29614984, 2018). "For TINCR, this lncRNA is induced by SP1 and promotes cell proliferation in gastric cancer and oesophageal squamous cell carcinoma, a finding that is in accordance with our results in breast cancer." (PMID 28738804, 2017). "Finally, the knockdown of TINCR, DSCAM-AS1 or HOTAIR inhibited breast cancer cell proliferation, increased apoptosis and inhibited cell cycle progression in vitro." (PMID 28738804, 2017). "Some researchers found that a higher TINCR level is correlated with poor survival in non-small-cell lung cancer (NSCLC), gastric cancer (GC), colorectal cancer (CRC), hepatocellular carcinoma (HCC), and breast cancer, because TINCR promotes cell apoptosis and migration." (PMID 32185226, 2020). "However, the expression pattern and involvement of TINCR in breast cancer has not been fully investigated." (PMID 29614984, 2018).
gastric cancer (29 papers, 2016 to 2024). A primary or metastatic malignant neoplasm involving the stomach. "A study by Ma et al20 found that SNPs of the lncRNA TINCR were significantly associated with decreased gastric cancer susceptibility by decreasing its gene expression levels." (PMID 31124188, 2019). "TINCR, a 3.7 kb long non coding RNA, was associated with cell differentiation in keratinocyte and gastric cancer cells." (PMID 27009809, 2016). "The lncRNA TINCR is strongly upregulated in gastric cancer, and promotes the growth of gastric cancer cells by regulating the expression of KLF2." (PMID 33732285, 2021). "For example, the TF E2F1 evokes the TINCR transcriptional activity and hastens gastric cancer progression through activating the TINCR/STAU1/CDKN2B axis." (PMID 34721660, 2021). "It has been demonstrated that two variants of TINCR (rs2288947 and rs8105637) are significantly correlated with the susceptibility and lymph node metastasis of colorectal cancer; the lincRNA TINCR rs2288947 G allele and rs8113645 A allele genotypes could reduce the risk of gastric cancer." (PMID 32523949, 2020). "In gastric cancer, the results of in vivo studies were consistent with the proposed oncogenic role of TINCR from cell line studies since two independent studies showed decreased tumor growth following TINCR knock-down in xenograft animal models." (PMID 32695943, 2020). "This transcription factor enhances growth of gastric cancer cells via induction of TINCR expression." (PMID 32695943, 2020). "TINCR silencing in human gastric cancer cell lines has decreased cell proliferation and colony formation." (PMID 32695943, 2020). "The oncogenic role of TINCR in gastric cancer cells is mediated through its interaction with STAU1 protein." (PMID 32695943, 2020). "Expression of TINCR has been significantly higher in gastric cancer cell line compared with a human gastric epithelial cell line." (PMID 32695943, 2020). "In gastric cancer, lncRNA TINCR regulates cell proliferation and apoptosis through binding to STAU1 to affect KLF mRNA stability." (PMID 28881797, 2017). "In human gastric carcinoma, up-regulated TINCR was found to contribute to oncogenesis and cancer progression through influencing cell proliferation and apoptosis." (PMID 28546230, 2017). "TINCR is also strongly overexpressed in human gastric cancer (GC) and contributes to carcinogenesis and tumor progression." (PMID 27893425, 2016). "E2F1 could induce TINCR transcriptional activity and accelerated the progression of gastric cancer by activating the TINCR/STAU1/CDKN2B signaling axis." (PMID 32851080, 2020). "Intriguingly, an integrated analysis of long non-coding RNA competing interactions in 361 gastric cancer indicated that TINCR might function as ceRNA with multiple potential miRNAs." (PMID 29614984, 2018). "TINCR was upregulated in human gastric carcinoma, and TUG1 was upregulated in many cancer tissues and cells; therefore, the increased expression of LUCAT1, TINCR, and TUG1 might not be specific to ACBP and ASLB treatments." (PMID 29156779, 2017). "On the contrary, TINCR promotes the proliferation of gastric cancer cells." (PMID 27893425, 2016). "Moreover, E2F1 enhances expression of TINCR in gastric cancer cells." (PMID 32695943, 2020). "However, TINCR is strongly upregulated in human gastric carcinoma (GC) and promoted cell growth." (PMID 27009809, 2016). "The research discovered significant increase of plasma lncRNA (TINCR, CCAT2, AOC4P, BANCR, and LINC00857) in gastric cancer cell lines." (PMID 33473276, 2021). "Similarly, lncRNAs, such as H19, TINCR, AOC4P, BANCR, LINC00857, and CCAT2, are detectable in body fluids and can be used to efficiently differentiate gastric cancer patients from healthy controls." (PMID 34885213, 2021).
colorectal cancer (16 papers, 2016 to 2023). A primary or metastatic malignant neoplasm that affects the colon or rectum. "However, another study from Li group displayed the anti-tumor activity of TINCR in colorectal cancer, wherein loss of TINCR expression promoted proliferation, metastasis through activating EpCAM cleavage." (PMID 29614984, 2018). "However, in colorectal cancer, the loss of TINCR expression promotes proliferation and metastasis by activating EpCAM cleavage." (PMID 28738804, 2017). "Moreover, a study by Zheng et al19 found that lncRNA TINCR polymorphisms were associated with the progression of colorectal cancer, and SNP rs2288947 may be a biomarker with the occurrence and progression of colorectal cancer." (PMID 31124188, 2019). "For example, the overexpression of the lncRNA TINCR inhibits colorectal cancer (CRC) cell proliferation and promotes apoptosis." (PMID 35799605, 2022). "TINCR overexpression inhibits the proliferation and metastasis of colorectal cancer cells by promoting EpCAM cleavage." (PMID 34187411, 2021). "LncRNA TINCR is downregulated in colorectal cancer, and overexpression of TINCR can inhibit the metastasis and proliferation of cancer cells." (PMID 32025520, 2020). "TINCR could act as a miR7‐5p sponge and silencing of TINCR suppressed proliferation, migration, and invasion in colorectal cancer cells." (PMID 31823440, 2020). "We relied on Oncomine, a cancer microarray database and web-based data-mining platform, to identify the expression level of TINCR in colorectal cancer tissues, and the result indicated that TINCR was significantly downregulated in colorectal cancer tissues comparing with adjacent tissues." (PMID 27009809, 2016).
bladder cancer (11 papers, 2016 to 2022). "Another study revealed that lncRNA TINCR rs2288947 A > G con predict increased bladder cancer risk and rs8113645 C > T is associated with decreased susceptibility." (PMID 35012438, 2022). "In bladder cancer, the lncRNA TINCR rs2288947 A > G variation was associated with increased expression of lncRNA TINCR in cancer tissues, and the rs8113645 C > T was associated with decreased expression." (PMID 34970542, 2021). "Moreover, the high expression of TINCR was associated with tumor metastasis and advanced tumor, metastasis stage, as well as reduced overall survival rates of patients with bladder cancer." (PMID 35525925, 2022). "For example, in bladder cancer, lncRNA TINCR promotes tumor proliferation and invasion by regulating miR-7 and mTOR." (PMID 36157234, 2022). "Further investigation revealed that microRNA-7 was negatively mediated by TINCR in bladder cancer cells." (PMID 35525925, 2022). "Silencing of TINCR expression significantly increased miR-7 expression and reduced bladder cancer cell proliferation, migration, and invasion, while knockdown of miR-7 expression reversed the inhibitory effects of TINCR downregulation on bladder cancer cells." (PMID 35525925, 2022). "Silencing TINCR by small interfering RNA can significantly inhibit bladder cancer cell proliferation and migration, thereby inhibiting the further development of bladder cancer." (PMID 34187411, 2021). "The overexpression of TINCR in the laryngeal cancer cell line TU212 significantly inhibited cancer cell proliferation, migration, and invasion, whereas TINCR knockdown promoted proliferation and invasion, which was consistent with research in bladder cancer." (PMID 34187411, 2021). "TINCR expression was significantly up-regulated in bladder cancer tissues and cells, showing strongly increased TINCR expression level in the higher tumor stage." (PMID 28546230, 2017). "In this study, we observed that TINCR was up-regulated in bladder cancer tissues and cells and contributed to oncogenesis and cancer progression." (PMID 27586866, 2016). "However, there is also evidence that in bladder cancer, TINCR promotes tumorigenesis and cancer progression by regulating cell proliferation and apoptosis." (PMID 34187411, 2021). "In conclusion, our findings demonstrated that knockdown of lncRNA-TINCR could inhibit the malignant phenotypes of bladder cancer cells, and TINCR may be used as a potential therapeutic target for bladder cancer." (PMID 27586866, 2016).
glioma (11 papers, 2017 to 2024). A benign or malignant brain and spinal cord tumor that arises from glial cells (astrocytes, oligodendrocytes, ependymal cells). "Other studies in glioma, prostate cancer and retinoblastoma indicated a tumor suppressor role for TINCR." (PMID 32695943, 2020). "However, other studies have demonstrated down-regulated of TINCR in glioma, retinoblastoma and prostate cancer." (PMID 32695943, 2020). "Our data suggest that TINCR expression could be a valuable marker of prognosis and malignant progression of glioma." (PMID 28546230, 2017). "Thus, TINCR has been shown to suppress glioma growth in vivo." (PMID 32695943, 2020).
hepatocellular carcinoma (10 papers, 2017 to 2024). A malignant tumor that arises from hepatocytes. "For example, TINCR can promote hepatocellular carcinoma proliferation and invasion via regulating STAT3 signaling." (PMID 35067169, 2022). "We investigate the role of lncRNA TINCR in miR-375/ATG7-mediated regulation of hepatocellular carcinoma proliferation and invasion." (PMID 36157234, 2022). "TINCR (terminal differentiation-induced lncRNA) modulates cancer cell behavior in many human malignancies, such as hepatocellular carcinoma (HCC)." (PMID 34057016, 2021). "Next, the levels of TINCR and TCPTP in hepatoma cell lines were measured, and the results showed that the expression of TINCR was higher in Hep3B and HCCLM3 cells than others." (PMID 34057016, 2021). "Hepatocellular carcinoma patients with high TINCR expression have shorter disease-free survival and overall survival than those with low TINCR expression." (PMID 32681722, 2020). "In contrast, TINCR is upregulated in hepatocellular carcinoma, and high TINCR expression is significantly correlated with tumor size, tumor differentiation, TNM stage, and vascular invasion." (PMID 32681722, 2020). "They found that TINCR is highly expressed in hepatocellular carcinoma (HCC) tissues and LCSCs, and its expression is crucial for the self-renewal and tumorigenesis of LCSCs." (PMID 38398197, 2024). "In hepatocellular carcinoma, miR-195-3p contributes to OXP-resistance through the TINCR/miR-195-3p/ST6GAL1/NF-κB signaling axis." (PMID 39401197, 2024).
lung carcinoma (10 papers, 2016 to 2025). "TINCR expression is upregulated in lung cancer, and upregulation is associated with the clinicopathological features of patients with tumors." (PMID 37051356, 2023). "In lung cancer cells, TINCR upregulation delayed cell invasion and proliferation by acting as a sponge for miR-544a." (PMID 40534867, 2025). "That is, lncRNA TINCR exerts anti-proliferation and invasion ability in lung cancer cells by regulating the miR-544a/FBXW7 axis." (PMID 40534867, 2025). "In lung cancer cells, TINCR upregulation retarded cell invasion and proliferation via acting as a sponge of miR-544a." (PMID 35928868, 2022). "Others reported that the overexpression of TINCR suppressed cell proliferation and invasion in lung cancer cells, tongue squamous cell carcinoma, and cutaneous squamous cell carcinoma." (PMID 32185226, 2020). "TINCR plays different roles in numerous tumor tissues; for example, it plays an inhibiting role in prostate cancer and other tumors, and plays a promotional role in non–small cell lung cancer." (PMID 37051356, 2023). "In lung cancer tissues, TINCR expression levels were downregulated." (PMID 35928868, 2022). "Therefore, further investigation is essential to determine the role of TINCR in lung cancer progression." (PMID 35928868, 2022). "Moreover, Kaplan-Meier analyses have shown correlation between expression levels of TINCR and patients survival in patients with lung cancer and HCC." (PMID 32695943, 2020). "The lncRNA TINCR, as a ceRNA, cleaves miR-544a from its target gene FBXW7 to regulate the proliferation and invasion of lung cancer cells." (PMID 36833217, 2023). "TINCR acted as a sponge for miR-544a and inhibited the proliferation and invasion of lung cancer cells, but miR-544a directly interacted with FBXW7 and reversed TINCR sponging miR-544a." (PMID 33412752, 2020). "In addition, lncRNAs such as MT1JP, MAGI2-AS3, PLAC2, TINCR, LINC00641, FENDRR (FOXF1 adjacent non-coding developmental regulatory RNA), TRHDE-AS1, and lncRNA-p21 act as tumor suppressors in lung cancer by sponging miRNAs." (PMID 33412752, 2020). "Several characterized cancer-associated lncRNAs were identified, such as PVT1, TINCR, and GAS5; while the well-known lung cancer-associated lncRNA, MALAT1 was not included." (PMID 26918601, 2016).
nasopharyngeal carcinoma (7 papers, 2020 to 2024). A carcinoma arising from the nasopharyngeal epithelium. "Furthermore, TINCR promotes nasopharyngeal carcinoma (NPC) proliferation and metastasis by upregulating acetyl-CoA levels, and ultimately promoting lipid biosynthesis." (PMID 33604287, 2020). "A novel lipid metabolic related lncRNA, TINCR, was identified to be significantly overexpressed in nasopharyngeal carcinoma (NPC), and can promote proliferation, metastasis and cisplatin resistance of NPC by affecting ACLY‐mediated de novo lipid biosynthesis." (PMID 37939296, 2024). "Additionally, TINCR can interact with ATP-Citrate Lyase (ACLY), BRAF, and Staphylococcal Nuclease and Tudor Domain Containing 1 (SND1) in nasopharyngeal cancer, non-small cell lung cancer, and post-burn skin fibroblasts, respectively." (PMID 34057016, 2021).